LARRPM (LINC00240 antisense RNA regulating promoter methylation)
Gene: Long non-coding RNA gene on chromosome 6 (26,966,975 to 27,069,510, reverse strand). Ensembl gene ENSG00000287966.
Diseases named in the same sentence as LARRPM in open-access papers:
LARRPM is named in the same sentence as 6 diseases in open-access papers, as found by Europe PMC text mining. Sharing a sentence is not in itself a finding about the gene and the disease. The quoted sentences say what the papers report.
asthma (1 paper, 2022). "First, some lncRNAs such as MIR155HG, lnc-BAZ2B, and LARRPM studied in asthma, COPD, and lung cancer studies are based on a small sample size at present." (PMID 36685535, 2022).
lung carcinoma (1 paper, 2022). "LARRPM expression in lung tissues is negatively associated with advanced stage and poor survival in patients with lung cancer due to its ability to inhibit M2 polarization." (PMID 36685535, 2022).
cancer (1 paper, 2022). A tumor composed of atypical neoplastic, often pleomorphic cells that invade other tissues. "Taken together, these findings suggested that LARRPM restricted LUAD progression via regulating both cancer cells and macrophages." (PMID 36221069, 2022). "The genomic localization of LARRPM was at the anti-sense strand of LINC00240, which has been reported to play various roles in different cancers." (PMID 36221069, 2022).
infection (1 paper, 2022). The state of being infected such as from the introduction of a foreign agent such as serum, vaccine, antigenic substance or organism. "To further investigate the roles of LARRPM in LUAD, we constructed HCC827 cells with LARRPM stable silencing via infection by two independent LARRPM-specific lentivirus shRNAs." (PMID 36221069, 2022).
tumor (1 paper, 2022). "Our findings suggest that LARRPM functions as a tumor repressor in LUAD through regulating both LUAD cells and TAMs." (PMID 36221069, 2022). "Collectively, these findings suggested that LARRPM exerted tumor suppressive roles in LUAD in vitro." (PMID 36221069, 2022). "Low expression of LARRPM was also correlated with large tumor size, local invasion and advanced TNM stages in our cohort." (PMID 36221069, 2022). "Take together, these findings suggested that LINC00240 at least partially mediated the tumor suppressive roles of LARRPM in LUAD." (PMID 36221069, 2022). "Low expression of LARRPM was correlated with large tumor size, local invasion, advanced TMN stage, and poor prognosis of patients with LUAD." (PMID 36221069, 2022). "In vivo xenograft assays showed that LARRPM suppressed LUAD tumor growth and metastasis, repressed LUAD cell proliferation and induced LUAD cell apoptosis in vivo." (PMID 36221069, 2022). "LARRPM was observed to act as a tumor suppressor in LUAD through regulating both LUAD cells and macrophages." (PMID 36221069, 2022). "To investigate whether LINC00240 mediates the tumor suppressive roles of LARRPM in LUAD, we stably depleted LINC00240 expression in A549 cells with LARRPM stable overexpression." (PMID 36221069, 2022).
LARRPM also shares sentences with these, for which no sentence is quoted: lung adenocarcinoma (1 paper).